MAFF (MAF bZIP transcription factor F)
Description:
Since they lack a putative transactivation domain, the small Mafs behave as transcriptional repressors when they dimerize among themselves. However, they seem to serve as transcriptional activators by dimerizing with other (usually larger) basic-zipper proteins, such as NFE2L1/NRF1, and recruiting them to specific DNA-binding sites. Interacts with the upstream promoter region of the oxytocin receptor gene. May be a transcriptional enhancer in the up-regulation of the oxytocin receptor gene at parturition.
Synonyms: hMafF; U-MAF
Tractability: PROTAC: ubiquitination databases record sites on it; its protein half-life has been measured.
Gene: Protein-coding gene on chromosome 22 (38,200,767 to 38,216,511, forward strand). Ensembl gene ENSG00000185022.
Subcellular location: Nucleus
Subcellular location (Human Protein Atlas): Nucleoplasm; Mitochondria
Pathways (Reactome):
Hemostasis: Factors involved in megakaryocyte development and platelet production
Gene Ontology:
Molecular function: DNA-binding transcription activator activity, RNA polymerase II-specific; protein binding; sequence-specific DNA binding; sequence-specific double-stranded DNA binding; DNA-binding transcription factor activity, RNA polymerase II-specific; RNA polymerase II cis-regulatory region sequence-specific DNA binding; DNA binding; DNA-binding transcription factor activity
Biological process: positive regulation of transcription by RNA polymerase II; negative regulation of transcription by RNA polymerase II; parturition; regulation of epidermal cell differentiation; regulation of transcription by RNA polymerase II; regulation of DNA-templated transcription
Cellular component: nucleoplasm; RNA polymerase II transcription regulator complex; chromatin; nucleus
Genetic constraint (gnomAD): Loss-of-function variants: 8 observed, 4.55 expected, observed/expected ratio (o/e) 1.76, 90% interval 0.92 to 1.95. That is too few expected variants to judge how well the gene tolerates losing a copy. Missense variants: 190 observed, 193.32 expected, observed/expected ratio (o/e) 0.98, 90% interval 0.87 to 1.11. Synonymous variants: 113 observed, 93.71 expected, observed/expected ratio (o/e) 1.21, 90% interval 1.03 to 1.41.
Homologues: Orthologues: chimpanzee MAFF (99% identical), macaque MAFF (98% identical), dog MAFF (93% identical), pig MAFF (93% identical), rabbit MAFF (91% identical), mouse Maff (88% identical), rat Maff (88% identical), tropical clawed frog maff (62% identical), zebrafish maff (54% identical), Drosophila melanogaster tj (35% identical), Drosophila melanogaster maf-S (34% identical), Caenorhabditis elegans maf-1 (25% identical). Paralogues in human: MAFK (63% identical), MAFG (62% identical), MAF (41% identical), MAFB (38% identical), MAFA (36% identical), NRL (34% identical).
Diseases named in the same sentence as MAFF in open-access papers:
MAFF is named in the same sentence as 54 diseases in open-access papers, as found by Europe PMC text mining. Sharing a sentence is not in itself a finding about the gene and the disease. The quoted sentences say what the papers report.
breast carcinoma (7 papers, 2021 to 2026). "In this study, we identify the transcription factor v-maf musculoaponeurotic fibrosarcoma oncogene homolog F (MAFF) as a key regulator that promotes breast cancer progression while simultaneously sensitizing tumor cells to ferroptosis." (PMID 42209456, 2026). "Here, the authors screened several hypoxia inducible genes and identified the oncogenic role of MAFF in breast cancer metastasis and that it activates IL11/STAT3 pathway." (PMID 34262028, 2021). "This study demonstrates the oncogenic role of MAFF as an activator of the IL11/STAT3 pathways in breast cancer." (PMID 34262028, 2021). "Hypoxia-induced increases in MAFF levels were observed in a number of breast cancer cell lines by wetsern blotting." (PMID 34262028, 2021). "Collectively, our study identifies MAFF as a transcriptional switch linking iron homeostasis and lipid metabolism to ferroptotic vulnerability, highlighting its potential as a biomarker and therapeutic target in basal-like breast cancer." (PMID 42209456, 2026). "Finally, survival analysis of breast cancer patients indicated that expression of both MAFF and BACH1 or MAFF, BACH1, and IL11 was significantly correlated with distant metastasis-free survival, further strengthening the prognostic significance of MAFF/IL11 pathways." (PMID 34262028, 2021). "MafG accelerates cell proliferation and inhibits cell apoptosis in lung adenocarcinoma, while MafF promotes tumor invasion through heterodimerizing with Bach1 and activating the IL11/STAT3 pathway in breast cancer." (PMID 37491302, 2023). "Specifically, TOM1L1 and ESR1 were highly expressed, but MAFF, TNS1, EFEMP2, and TRIM31 were significantly downregulated in breast cancer." (PMID 34151731, 2021). "Only six genes were differentially expressed between controls and breast cancer cases in GEO datasets (GSE15852, GSE115144, and GSE109169), and the SNPs rs4829 and rs9610915 were located next to the m6A modification sites in the 3ʹUTRs of TOM1L1 and MAFF, respectively." (PMID 34151731, 2021).
hepatocellular carcinoma (5 papers, 2018 to 2024). A malignant tumor that arises from hepatocytes. "MAFF has been postulated as a possible tumour suppressor regulated by miRNA-224-5p in hepatocellular carcinoma." (PMID 39594467, 2024). "This miRNA has been reported as an oncomiR and biomarker in several types of cancer; additionally, miR-224-5p binding to MAFF occurs in hepatocellular carcinoma." (PMID 39594467, 2024). "For instance, enforced expression of circ-ITCH inhibited the proliferation and induced apoptosis of hepatocellular carcinoma cells via upregulating MafF expression by acting as a miR-224-5p sponge." (PMID 36750911, 2023). "For example, bladder cancer patients with high MAFF expression have a higher survival rate, suggesting a cancer suppression effect, yet it remains controversial whether MAFF has a tumor suppressor effect in hepatocellular carcinoma." (PMID 33315534, 2021).
atherosclerosis (4 papers, 2021 to 2025). A disease characterized by the build-up of fatty material and calcium deposition in the arterial wall resulting in partial or complete occlusion of the arterial lumen. "MAFF’s dual role of MAFF under varying conditions suggests its potential in regulating the balance between inflammation and lipid metabolism, which is critically involved in the development and progression of atherosclerosis and cardiovascular disease." (PMID 41377395, 2025).
COVID-19 (4 papers, 2021 to 2024). A disease caused by infection with severe acute respiratory syndrome coronavirus 2. "In the present study, we succeeded in identifying 3 key genes, DDIT3, MAFF, and PNRC1, which are possibly involved in the development of both OA and COVID-19 and have high diagnostic value for OA and COVID-19." (PMID 37283761, 2023). "On the other hand, 450 (22.96%) and 63 (41.18%) DEGs were downregulated (Down) in COVID-19 patients and recovered subjects, respectively, and of them, only 12 genes (i.e., MAFF, ARHGEF12, DCUN1D3, DR1, MT-CO1)." (PMID 36059456, 2022). "Data from a single-cell transcriptomic analysis of PBMC in severe COVID-19 patients showed a significant enhancement of MAFF and AREG expression in monocytes." (PMID 34572439, 2021). "In this study, we identified 26 common genes between OA and COVID-19 by WGCNA and screened three key genes DDIT3, MAFF, and PNRC1 using machine learning algorithms." (PMID 37283761, 2023). "As shown in the UMAP and violin plots, in COVID-19 patients, DDIT3 was highly expressed in neutrophils and cDC cells, MAFF was highly expressed in neutrophils and GZMK NK cells, and PNRC1 was highly expressed in almost all immune cells and blood cells." (PMID 37283761, 2023). "Collectively, these results suggest that DDIT3, MAFF, and PNRC1 play important roles in OA and COVID-19 pathogenesis, while STX11 lacks specificity." (PMID 37283761, 2023). "In addition, we screened 3 key genes, DDIT3, MAFF, and PNRC1, and uncovered that key genes are possibly involved in the pathogenesis of OA and COVID-19 through high expression in neutrophils." (PMID 37283761, 2023). "In addition, high MAFF expression can upregulate ACE2 and thus increase the inflammatory response in COVID-19 patients, resulting in poor prognosis." (PMID 37283761, 2023). "The MAFF-promoter region showed increased accessibility in acute COVID-19 monocytes in comparison to monocytes from post-COVID-19 and HC subjects, whereas CD4 chromatin opening was reduced in monocytes from the acute disease, intermediate in post-COVID-19 monocytes and maximum in HC." (PMID 34572439, 2021). "Comparing the results of the analysis with those of the HPA database, we found that the expression of DDIT3, MAFF, and PNRC1 in immune cells was the same as normal, indicating that the expression pattern of key genes in immune cells did not change during the progression of COVID-19." (PMID 37283761, 2023).
diabetes (4 papers, 2022 to 2025). "For example, by inhibiting MafF, the pancreatic beta cells loss its function in diabetes; it also regulates endoplasmic reticulum stress as well as autophagy in diffuse large B-cell lymphoma; and human glucagon expression." (PMID 35444548, 2022). "There is limited information regarding the specific role of MAFF proteins in human diseases, but they have been implicated in various pathological conditions such as cancer, diabetes, immune system disorders and neurodegenerative diseases such as Alzheimer's disease and Parkinson's disease." (PMID 40499265, 2025). "The high expression groups of PENK, EFEMP2, UBAP1, MAFF and KLF4 were mainly concentrated on diabetes mellitus (DM)." (PMID 38332532, 2024).
glioma (3 papers, 2021 to 2025). A benign or malignant brain and spinal cord tumor that arises from glial cells (astrocytes, oligodendrocytes, ependymal cells). "However, despite its cytoprotective function, decreased MAFF expression is observed in various tumor types, and MAFF suppression has been shown to reduce metastatic potential, including in gliomas." (PMID 41304780, 2025).
lung carcinoma (3 papers, 2021 to 2025). "Compared with normal tissues, the expression of ADM2, CLIC6, KIF20A, LAD1, MUC5B, and TNS4 was up-regulated, and the expression of ATG16L2, KCNK3, MAFF, NKD1, and SPATA13 was down-regulated in lung cancer tissues." (PMID 34804921, 2021). "In addition, overexpression of MAFF in A549 human lung cancer cells, which exhibit a non-invasive phenotype, displayed increased tumor cell invasion and migration." (PMID 34262028, 2021).
melanoma (3 papers, 2017 to 2024). A malignant, usually aggressive tumor composed of atypical, neoplastic melanocytes. "For example, of the 16 total genes driving the association between melanoma and nevus count, only two (MTAP and ERVFRD‐3) were shared by all three tissues, and six (MAFF, HEBP1, HTR7P1, EMP1, GPRC5A, C9orf66) were specific to melanocyte." (PMID 38308491, 2024).
bladder cancer (2 papers, 2021 to 2023). "On the contrary, the enhanced expression of MafF works as a better prognostic indicator in bladder cancer." (PMID 36750911, 2023).
colon cancer (2 papers, 2021). "On the other hand, it also indicated that two genes, namely, MT2A and MAFF, might act an important role in the development and progression of colon cancer and the prognostic model based on these genes would be valuable for clinical application." (PMID 34917146, 2021).
fibrosarcoma (2 papers, 2020 to 2023). A malignant mesenchymal fibroblastic neoplasm affecting the soft tissue and bone. "The small musculoaponeurotic fibrosarcoma (sMaf) proteins MafF, MafG, and MafK are basic region leucine zipper- (bZIP-) type transcription factors and display tissue- or stimulus-specific expression patterns." (PMID 33488846, 2020).
leukemia (2 papers, 2020 to 2021). A malignant (clonal) hematologic disorder, involving hematopoietic stem cells and characterized by the presence of primitive or atypical myeloid or lymphoid cells in the bone marrow and the blood. "The IMSGC GWAS and dSNP rs62420820 shows allele-specific TF binding differences for MafF and MafK in the leukemia cell line K562." (PMID 32012148, 2020).
liver cancer (2 papers, 2018 to 2022). An epithelial or non-epithelial malignant neoplasm that arises from the liver. "CircRNA activating MAFF (cia-MAF) was identified as a functional oncogenic circular RNA in liver cancer and liver tumor-initiating cells (TICs)." (PMID 35081965, 2022). "The ASO specific to cia-MAF displayed impaired self-renewal and metastatic capacities of liver cancer via promoting the expression of redox sensor-MAFF." (PMID 35081965, 2022).
lupus nephritis (2 papers, 2024 to 2025). Glomerulonephritis in the context of systemic lupus erythematosus. "This study explored the effect and mechanism of MAFF and HDAC6 on renal fibrosis and inflammation in lupus nephritis (LN)." (PMID 39412062, 2024).
osteosarcoma (2 papers, 2021 to 2024). A usually aggressive malignant bone-forming mesenchymal neoplasm, predominantly affecting adolescents and young adults. "According to the Kaplan-Meier (KM) survival analysis of 8 modeled genes, elevated expression levels of COL5A2, COX6A2, UQCRB, SFXN4, FAM162A and MAFF sharply shortened the survival time of osteosarcoma patients." (PMID 39569192, 2024). "In this study, we explored the role of four genes (EFNA1, P4HA1, STC2, and MAFF) profiled in a previous study on osteosarcoma." (PMID 34337075, 2021). "Multivariate Cox regression analysis confirmed that these 8 identified genes, including 2 protective elements (SQOR and PFKFB2) and 6 hazardous factors (MAFF, COL5A2, FAM162A, UQCRB, SFXN4, and COX6A2), could independently predict the overall survival of osteosarcoma samples." (PMID 39569192, 2024).
Parkinson disease (2 papers, 2020 to 2025). A progressive degenerative disorder of the central nervous system characterized by loss of dopamine producing neurons in the substantia nigra and the presence of Lewy bodies in the substantia nigra and locus coeruleus. "In Parkinson's disease, MafF is differentially regulated in olfactory neurosphere-derived cells." (PMID 33488846, 2020).
age-related macular degeneration (1 paper, 2025). Age-related loss of vision in the central portion of the retina (macula), secondary to retinal degeneration. "We analysed the expression of MT1G, AKAP12 and MAFF in postmortem human retinas with documented age-related macular degeneration (AMD) with geographic atrophy and diabetic retinopathy (DR)." (PMID 40499265, 2025).
chronic kidney disease (1 paper, 2024). Impairment of the renal function secondary to chronic kidney damage persisting for three or more months. "RNAseq analysis in a previous study also reported MAFF as one of the downregulated genes in chronic kidney disease mouse models." (PMID 39412062, 2024).
diabetic retinopathy (1 paper, 2025). "Notably, in diseased human maculas (AMD and diabetic retinopathy samples) we observed elevated MT1G, AKAP12, and MAFF in Müller glia at the margins, suggesting that macular Müller cells can activate these pathways, but perhaps only in the face of significant stress or damage." (PMID 40499265, 2025).
encephalitis (1 paper, 2025). An acute inflammatory process affecting the brain parenchyma. "Specifically, we identified six differentiallyexpressed immune genes—MET, KIT, IL1R2, MAFF, CD69, andCEBPD—between the encephalitis and non-encephalitis groups." (PMID 40985687, 2025).
influenza infection (1 paper, 2019). "We found that NK cells from Ebi3−/− as well as Il27ra−/− mice have reduced MafF expression with the highest fold change during influenza infection." (PMID 30899058, 2019). "We confirmed gene array data using RT-qPCR analyses of c-Maf, MafF, and MafK expression in sorted NK cells from influenza-infected WT and Ebi3−/− mice." (PMID 30899058, 2019).
Insulin resistance (1 paper, 2013). Increased resistance towards insulin, that is, diminished effectiveness of insulin in reducing blood glucose levels. "HF IU increased hepatic expression of genes associated with insulin resistance (TNFα, SOCS3, PAI-1) and cellular stress (TXM, MAFF and DUSP)." (PMID 23690974, 2013).
legionellosis (1 paper, 2021). Any disease caused by Legionella bacteria. "Interfering a series of human diseases pathways including legionellosis, toxoplasmosis, and measles and some key factors such as MAFF, HSPA1A, HSPA1B, AOC1, and MX2, high doses of moxa smoke influenced the function of rat lungs." (PMID 34961819, 2021).
mastitis (1 paper, 2014). Inflammation of breast tissue during lactation or postpartum due to an obstructed duct or infection. "Two of them were related to mastitis in a disease-induced mouse-model study: BID (BH3 interacting domain death agonist), which is a pro-apoptotic induced gene, and MAFF (v-maf avian musculoaponeurotic fibrosarcoma oncogene homolog F), which is related to cell proliferation." (PMID 24788864, 2014).
ovarian carcinoma (1 paper, 2021). A malignant neoplasm originating from the surface ovarian epithelium. "In OVCAR8, an invasive ovarian cancer cell line with high NRF2 expression, loss of MAFF reduced cell invasion." (PMID 34262028, 2021).
renal fibrosis (1 paper, 2024). A final common manifestation of a wide variety of chronic kidney diseases characterized by glomerulosclerosis and tubulointerstitial fibrosis. "To determine the effect of MAFF on renal fibrosis and inflammation, we first detected MAFF expression after IL-33 treatment." (PMID 39412062, 2024). "Above results demonstrated MAFF was decreased in renal tissues of LN mice whereas overexpression of MAFF can attenuate renal fibrosis and inflammation of LN mice." (PMID 39412062, 2024). "Although MAFF overexpression can suppress renal fibrosis and inflammation, the mechanism herein remains to be determined." (PMID 39412062, 2024). "Overall, HDAC6 aggravated renal fibrosis and inflammation in mice with LN via the MAFF/KLF5 signaling axis." (PMID 39412062, 2024). "In this study, we explored the role of the HDAC6/MAFF/KLF5 axis in renal fibrosis and inflammation using both in vivo and in vitro experiments with the expectation to provide a theoretical basis for proposing new treatment approaches for LN patients, especially for pediatric patients." (PMID 39412062, 2024). "Considering the finding of our previous study that KLF5 promotes renal fibrosis in MRL/lpr mice, it is reasonable to speculate the possible effect of HDAC6/MAFF/KLF5 axis in LN." (PMID 39412062, 2024). "This study explored the possible effect and involvement of HDAC6 in regulating renal fibrosis and inflammation in LN using both in vivo and in vitro experiments and highlighted the promotive effect of HDAC6 on LN progression through regulating the MAFF/KLF5 axis." (PMID 39412062, 2024).
thyroid papillary carcinoma (1 paper, 2023). "MafF is also recognized as a potential biomarker in HCC and thyroid papillary carcinoma patients." (PMID 36750911, 2023).